INS (insulin)
Diseases named in the same sentence as INS in open-access papers (continued):
Sharing a sentence is not in itself a finding about the gene and the disease.
diabetes (continued). "In line with this thought, it has been proposed that hypothalamic inflammation is a potential cause of leptin and insulin resistance in the hypothalamus of rodents and patients with obesity and diabetes." (PMID 30618568, 2018). "The GG genotype of rs2281939 was associated with a higher risk of diabetes at baseline, an earlier onset of diabetes, and higher steady-state plasma glucose levels in the modified insulin suppression test." (PMID 30002559, 2018). "Only two changes were observed during the subgroup analyses: increasing severity and duration of diabetes were each associated with lower HbA1c levels in patients with T2DM taking insulin." (PMID 29980691, 2018). "High PPWR is associated with reduced insulin sensitivity, hypertension, and later development of type 2 diabetes mellitus and cardiovascular disorders." (PMID 29310617, 2018). "Diabetes during pregnancy elevates the mother's blood glucose and insulin levels, causing insulin to circulate from the mother to baby, which can lead to excessive fat deposits and macrosomia." (PMID 30174954, 2018). "High glycaemic index diets have been linked to the development of diverse metabolic diseases such as obesity, decreased insulin sensitivity, an elevated risk of developing diabetes and are a risk factor for coronary heart disease." (PMID 29495516, 2018). "Diabetes mellitus is characterized as a group of metabolic diseases associated with the body’s inability to produce or react to insulin, leading to prolonged high blood glucose." (PMID 30470798, 2018). "Type 1 diabetes mellitus [T1DM] results from an absolute deficiency of insulin, while type 2 diabetes mellitus [T2DM] is due to insulin resistance." (PMID 30228829, 2018). "The tocotrienol-rich fraction (TRF) also prevented muscle atrophy associated with diabetes by regulating insulin signaling via the AMPK/SIRT1/PGC-1α pathways in type 2 diabetic mice." (PMID 30275871, 2018). "A study has shown that muscle fiber components are related to insulin resistance, while exercises can increase the amount of myosin fibers, thereby reducing the risk of diabetes." (PMID 30302116, 2018). "Cardiovascular complications are recognized as the primary cause of mortality in subjects with diabetes mellitus (DM), characterized by hyperglycemia which is determined by a defect of insulin secretion, insulin action, or both." (PMID 30622968, 2018). "GSK3 members participate in apoptosis, cell cycle control, insulin action, neuronal cell death, and developmental regulation processes and are associated with various disorders including diabetes, inflammation, neurological, and neoplastic diseases." (PMID 30020984, 2018). "Type 1 diabetes mellitus is caused by a destruction of the β-cells of the islands of Langerhans in the pancreas, which produce insulin." (PMID 29898693, 2018). "During diabetes or insulin resistance, failure of insulin-stimulated glucose uptake by fat and muscle causes high glucose concentration in blood." (PMID 29558444, 2018). "Beta cells then release insulin continuously, causing insulinopenia later in life, which can predispose a patient to develop diabetes." (PMID 29637032, 2018). "In fact, diabetes or obesity is highly associated with glucose intolerance, insulin insensitivity, and increased risk for AD53." (PMID 29703936, 2018). "Previous studies have reported that several risk factors, including HbA1c level, duration of diabetes, hypertension, hyperlipidaemia, body mass index (BMI), sex, and insulin treatment, are involved in the development of DR." (PMID 29682578, 2018). "TZDs are known to improve systemic insulin sensitivity in animal models of obesity-linked insulin resistance and diabetes by enhancing glucose disposal in skeletal muscle and suppressing gluconeogenesis in the liver." (PMID 30524482, 2018).
diabetes (continued). "Given the genetic association of SORCS1 with diabetes and the recently documented role for this receptor in insulin secretion, we also analyzed the systemic glucose metabolism in S1/3 KO mice fed a normal chow." (PMID 29440124, 2018). "Generally, long-term diabetes duration is associated with a lesser capacity for insulin secretion and these participants tend to have a lower BMI as compared to participants with shorter diabetes duration." (PMID 29549238, 2018). "In order to study the possible enrichment/depletion of certain fatty acid constituents of TAGs in association with insulin sensitivity or diabetes, an enrichment analysis based on the Wilcoxon sum of the ranks test was conducted (refer to “Methods” section)." (PMID 29940972, 2018). "Further, first-degree family history of diabetes is associated with impaired insulin secretion and action." (PMID 29274011, 2018). "Diabetes mellitus is a metabolic disease caused by the body's incapacity to produce insulin or by the ineffective use of the insulin produced." (PMID 30073019, 2018). "Insulin plays a special role among these regulators, controlling many aspects of carbohydrate and lipid metabolism, and disorders in insulin signaling and regulation cause diabetes." (PMID 30197596, 2018). "These mutations disrupt SP cleavage, leading to reduced insulin secretion in a dominant fashion, resulting in ER stress and β cell apoptosis, in a form of diabetes termed mutant insulin gene–induced diabetes of youth (MIDY)." (PMID 29864031, 2018). "Microbial intestinal changes have been linked to changes in insulin sensitivity and in glucose metabolism and the development of metabolic syndrome with diabetes and subsequent cardiovascular complications." (PMID 30539026, 2018). "Fast and sensitive detection of this hormone is very important not only because of the diagnostic of diabetes but also because of the improper use of insulin as a doping drug in competitive sports." (PMID 30042294, 2018). "The simulation predicts individuals in the simple insulin infusion group to have considerable reductions in lifetime risk of developing diabetes-related complications compared to the MDI group." (PMID 32685574, 2018). "Insulin overdose in diabetics can result to severe hypoglycemia and coma while under-dose can cause diabetes ketoacidosis; both can have fatal consequences." (PMID 29929949, 2018). "Diabetes mellitus (DM) is a metabolic and chronic disease with multifactorial etiology, caused by defects in insulin secretion and/or action and presenting hyperglycemia as a common manifestation." (PMID 29652940, 2018). "Diabetes is a chronic disease caused by hyperglycemia due to absolute insulin deficiency or abnormal insulin function." (PMID 30395577, 2018). "Administration of MI is more effective in obese patients who have high fasting serum insulin or hyperinsulinemia and familiar predisposition to diabetes." (PMID 30513929, 2018). "Infants affected by this early onset of diabetes have mutations in one copy of the gene that encodes insulin." (PMID 30412050, 2018). "A majority of studies have investigated the association between vitamin D and glucose and insulin homeostasis among the patients with diabetes, while few studies have paid attention to this association among nondiabetic adults." (PMID 30627160, 2018). "Regarding diabetes, we identified pronounced associations and risk factors in Qatari population including magnesium, chloride, c-peptide of insulin, insulin, and uric acid." (PMID 29650030, 2018). "It is an inbred model that spontaneously develops hyperglycemia, glycosuria and glucose intolerance resulting from genetic defects that cause gradual beta-cell degeneration, impaired insulin secretion, and eventual development of the diabetes." (PMID 29463026, 2018).
diabetes (continued). "Next to the single metabolite associations and the valine to PC ae C32:2 ratio, the ratio of alanine and glycine strongly associated with insulin sensitivity measured using the hyperglycaemic clamp and incident diabetes in the KORA S4_to_F4 cohort." (PMID 28936587, 2018). "Inadequate secretion or action of insulin causes diabetes, a metabolic disease characterized by high blood glucose, persistence of which will lead to the classical symptoms of polyuria, polydipsia and polyphagia." (PMID 30322036, 2018). "Diabetes mellitus is characterized by hyperglycemia, caused by the inability of the beta cells to maintain sufficient levels of circulating insulin." (PMID 30386256, 2018). "These include NeuroD1, which regulates both neuronal differentiation as well as insulin expression, and is associated with type 2 diabetes mellitus, an obesity-related complication reported in adults with PWS43,44." (PMID 29691382, 2018). "Diabetes is a disease caused by the inadequate production of insulin by the pancreas, or the inability to effectively utilize insulin." (PMID 30217075, 2018). "Accumulating evidence suggests that elevated SF levels is associated with higher fasting insulin levels, insulin resistance, and an increased risk of diabetes." (PMID 29425155, 2018). "Although recommendations for more prolonged observation exist, individuals on oral diabetes medications and long-acting insulin are often discharged when there is felt to be a low risk of recurrent hypoglycemic events." (PMID 29799604, 2018). "Although not completely elucidated, it is now acknowledged that the alterations of insulin signaling in AD and diabetes are associated." (PMID 30542257, 2018). "Our results also correspond to the observation that insulin treatment during a GDM pregnancy (reflecting its severity) increases diabetes risk in later life." (PMID 30210648, 2018). "Impaired insulin signaling, for instance in diabetes mellitus, increases the risk of epilepsy and cognitive disabilities." (PMID 29904337, 2018). "Factors such as the time course of diabetes and the use of insulin have also been negatively associated with QoL." (PMID 29764429, 2018). "Type 1 diabetes mellitus (T1DM) is the consequence of the autoimmune mediating pancreatic insulin-producing β cells damage and loss." (PMID 29416823, 2018). "Increasing prevalence of diabetes coupled with longer life expectancy, and thus longer diabetes duration, means there is an increasing elderly population on potentially hypoglycaemia-causing medications such as insulin and sulphonylureas." (PMID 28918198, 2018). "According to adjusted Cox regression model, cataract surgery, using OHA, and using insulin were risk factors for NPDR in all patients with diabetes." (PMID 30133506, 2018). "Several pathogenic processes are involved in the development of diabetes, range from autoimmune destruction of the pancreatic β-cells with consequent insulin deficiency to abnormalities that result in resistance to insulin action." (PMID 29572460, 2018). "Obese women have an increased risk for high insulin values and for developing diabetes mellitus type 2 postpartum." (PMID 29310617, 2018). "SeP causes insulin resistance and hyperglycemia in diabetes, and treatment with purified SeP protein impairs insulin signal transduction." (PMID 29547524, 2018). "This study suggested that subjects with GG genotype of rs2920502 in PPARγ, who had better early- and total-stage insulin secretion function and better serum lipid condition, had a decreased risk for diabetes in Chinese Han population of Beijing district." (PMID 29849618, 2018). "Since then, the biology of the insulin producing β-cells in the islet came under much scrutiny as the loss of β-cell function, hence the loss of insulin, was associated with diabetes." (PMID 29534517, 2018).
diabetes (continued). "Risk factors for death were: age (HR = 1.063), diabetes requiring insulin (HR = 2.832), creatinine concentration (HR = 1.005; all groups), age (HR = 1.11; female group), and elevated creatinine level (HR = 1.012; male group)." (PMID 28396904, 2018). "LADA, the most prevalent form of adult-onset autoimmune diabetes, is characterized by the presence of diabetes, associated pancreatic autoimmunity and more frequent need for insulin treatment than patients with type 2 diabetes." (PMID 30346951, 2018). "Diabetes mellitus is a growing public health issue, characterized by dysfunctional and/or loss of insulin-producing β cells; hence the urgent need for therapeutic agents that can promote function and maintenance of β cells." (PMID 30150605, 2018). "Diabetes is caused by loss or dysfunction of the insulin-secreting pancreatic β-cells, with autoimmune loss causing T1D, whilst in T2D, insulin secretion is defective, which in turn brings about an imbalance in glucose homeostasis and insulin resistance." (PMID 30007277, 2018). "Bothdyslipidemia and hyperglysemia contribute to loss ofß-cells function and impairment of insulin secretion inobesity and diabetes." (PMID 29308616, 2018). "In the European study, factors that were associated with increased obesity during the course of diabetes were higher insulin doses, female gender, low BMI at diabetes onset, intensified insulin therapy, pubertal diabetes onset, and long duration of diabetes." (PMID 29101482, 2017). "Diabetes is a multi-tissue metabolic disease caused by defects in insulin action, insulin secretion, or both, resulting in hyperglycemia." (PMID 28473845, 2017). "The expression and translocation of GLUT4 are highly regulated by insulin, and disruption of this regulatory process results in insulin resistance and an increased risk for developing diabetes." (PMID 28584820, 2017). "Several studies has showed that fruit and vegetable consumption is associated with lower glycosylated haemoglobin levels, greater insulin sensitivity, and a reduced risk of type 2 diabetes mellitus." (PMID 28587067, 2017). "There are two main forms of the disease: type 1 diabetes mellitus is an autoimmune disease caused by impaired insulin secretion resulting from the destruction of islet cells in the pancreas." (PMID 37168685, 2017). "The loss of insulin producing pancreatic beta-cells resulting from apoptotic cell death is a major problem in all forms of diabetes mellitus." (PMID 28469576, 2017). "Eight out of the 17 CpG sites selected by the elastic net analysis reside in genes that are associated with obesity, diabetes, or the insulin pathway by prior studies." (PMID 28068899, 2017). "Increased Igf1R expression in adipose tissue is associated with reduced incidence of diabetes, because it promotes insulin signalling and therefore favours fat storage over ectopic energy storage." (PMID 28212289, 2017). "There is considerable evidence to show that weight loss can improve insulin sensitivity and reduce the risk of diabetes and cardiovascular disease (CVD)." (PMID 29186908, 2017). "As a result, Cip/Kip family members, which are known to function as cell cycle inhibitors, are downregulated in β-cells, thereby promoting β-cell proliferation in mice with insulin-deficient diabetes." (PMID 27974246, 2017). "T2DM, the most common form of diabetes principally arising due to insulin resistance and reduced insulin activity is a risk for several complications, namely atherosclerosis, neuropathy, nephropathy, retinopathy and cardiovascular diseases." (PMID 28761062, 2017). "Our data support a novel mechanism in diabetes-associated PDAC by which transgelin-2 mediates proliferation of PDAC cells upon insulin stimulation." (PMID 28521289, 2017). "Diabetes is a strong risk factor for the progression of sarcopenia and insulin activity is critical to maintain the balance of muscle protein synthesis and degradation." (PMID 28246927, 2017).
diabetes (continued). "In mice, TNF-α and PA were administered to mimic risk factors during pre-diabetes and insulin-stimulated 18F-FDG uptake in the heart was evaluated by PET." (PMID 28304381, 2017). "In recent years, most research efforts have been focused on studying diabetes associated insulin-sensitizing adipokines, such as adiponectin (also known as Acrp30), vaspin visfatin, metrnl (also known as subfatin), and retinol binding protein 4 (RBP4)." (PMID 28659972, 2017). "We propose that deficiency of Grx1 and 5 is connected to impaired insulin secretion and beta-cell decay in diabetes mellitus type 2." (PMID 28542222, 2017). "Diabetes mellitus (DM) is a heterogeneous group of metabolic disorders characterized by hyperglycemia caused by defects in insulin action or insulin secretion." (PMID 28355348, 2017). "This study found a significant association between caregiver involvement in the diabetes-related tasks of insulin injection and BGM and good glycaemic control." (PMID 28606170, 2017). "For example, compared to other groups, many pathways associated with diabetes such as insulin resistance, type II diabetes mellitus and insulin signaling pathway are enriched in H007 group." (PMID 28178661, 2017). "Several years have passed since completion of the meta-analysis and recent clinical trials examining the effects of 100 % fruit juice consumption on glucose–insulin homeostasis provide further insight into the role of juice on biomarkers of diabetes risk." (PMID 29299307, 2017). "Diabetes mellitus (DM), commonly referred to as diabetes, is a group of chronic diseases associated with high levels of blood glucose resulting from deficits in insulin production, insulin action, or both." (PMID 29399644, 2017). "Premorbid insulin-requiring diabetes was associated with lower levels of c-peptide and higher plasma creatinine with greater levels of c-peptide." (PMID 28497374, 2017). "Here we show that β-cell-specific loss of mTORC1 causes diabetes and β-cell failure due to defects in proliferation, autophagy, apoptosis and insulin secretion by using mice with conditional (βraKO) and inducible (MIP-βraKOf/f) raptor deletion." (PMID 28699639, 2017). "Diabetes mellitus is characterized by a deficiency in the production or action of insulin, or both, resulting in increased blood glucose in untreated individuals." (PMID 27598977, 2017). "The interaction between the cryptochrome 1 (CRY1) rs2287161 G>C variant and several diabetes-related traits (fasting glucose and insulin, HOMA-IR and QUICKI index) has been studied in The Mediterranean and North American Cohort." (PMID 28574454, 2017). "Inverse associations between diabetes and MD were observed for women who controlled diabetes with diet or oral antidiabetic agents, while women taking insulin showed a positive association with having mixed/dense breasts, though statistically non-significant." (PMID 27832382, 2017). "Aberrant insulin production is a hallmark of diabetes resulting from autoimmune destruction of β-cells (type 1 diabetes; T1D) or hormone resistance by tissues absorbing glucose (type 2 diabetes; T2D)." (PMID 28839233, 2017). "While the systemic damage caused by diabetes is well described, only recently have researchers began to recognise the significance of insulin and insulin resistance for brain and cognitive health." (PMID 28093279, 2017). "Considering that impaired first-phase insulin in (pre-)diabetes is associated with impaired glucose tolerance, we investigated the effects of different dynamic features of first-phase insulin, including the peak level and the slope of the increase." (PMID 29118381, 2017). "Four potential risk factors related to diabetes were evaluated, including type 2 diabetes, fasting glucose, fasting insulin, and two-hour-postchallenge glucose." (PMID 28954281, 2017). "We first inquired if the HNF4A mutation or diabetes status prevented the differentiation of insulin+ cells in vitro." (PMID 28684784, 2017).